PADI4 (peptidyl arginine deiminase 4)
Diseases named in the same sentence as PADI4 in open-access papers (continued):
Sharing a sentence is not in itself a finding about the gene and the disease.
Sepsis (continued). "The cell percentage graph indicated that PADI4+ neutrophils, CD177+ neutrophils, and SNHG8+ neutrophils were significantly increased in sepsis tissues." (PMID 40666706, 2025). "While research has predominantly focused on the individual deletion of Padi2 or Padi4, the combined effect of Padi2 and Padi4 double KO (DKO; Padi2–/– Padi4–/–) on sepsis and its progression, particularly in the context of lung injury, is not well understood." (PMID 39405117, 2024). "Our study shows that Padi2–/– Padi4–/– double KO (DKO) improved survival, reduced lung injury, and decreased bacterial load in Pseudomonas aeruginosa (PA) pneumonia–induced sepsis mice." (PMID 39405117, 2024). "During sepsis, the bone marrow releases a large amount of immature granulocyte (IGs) through emergency granulopoiesis, such as CEACAM8+Neu, S100A8/9hiNeu, IL1R2+Neu, PADI4+Neu, MPO+Neu and cycling MK167+CYP1B1+Neu." (PMID 40356926, 2025).
Arthritis (39 papers, 2005 to 2025). Inflammation of a joint. "By predicting the interactions of CRP and OST with PADI4, a key arthritis-associated gene, PICKLE helps elucidate how these proteins contribute to inflammatory pathways." (PMID 40266392, 2025). "The GTTC haplotype in PADI4 was associated with an increased risk of developing arthritis (OR = 1.40, 95% CI = 1.12–1.74, p = 0.018) while three haplotypes (GTCG, ACTC, and ACTG) were associated with decreased risk (OR = 0.12 to 0.65, [p < 0.05])." (PMID 37759458, 2023). "Deficiency or inhibition of PADI4 reduces the formation and the size of NETs and alleviates arthritis symptoms in many models, except the murine K/BxN model." (PMID 33584645, 2020). "Padi4 deficient mice revealed the amelioration of arthritis severity in mouse arthritis models." (PMID 36823444, 2023). "The interaction between CRP, OST, and arthritis, specifically involving PADI4 (Peptidyl Arginine Deiminase 4), is an area of research focused on understanding the pathogenesis of arthritis." (PMID 40266392, 2025). "Computer-aided molecular design database predictions revealed complex interactions between CRP, OST, and PADI4, highlighting their roles in arthritis pathogenesis." (PMID 40266392, 2025). "In arthritis, the genetic variation of PADI2 and PADI4 can confer RA susceptibility, and they can aggravate arthritis by promoting the secretion of NETosis and inflammatory cytokines." (PMID 37020554, 2023). "Since a decrease in the number of CD11b+ cells was evident in GPI-immunized Padi4 KO mice, this shortage of IL-6 sources represents one possible explanation for the reduced arthritis severity in Padi4 KO mice." (PMID 26293116, 2015). "In the case of antibody-dependent arthritic models, Padi4 was dispensable for the arthritis effector phase." (PMID 26293116, 2015). "Taken together, we demonstrated diverse immunological modifications, including helper T cell development, cytokine production, and immune cell apoptosis in Padi4 KO mice, which played certain roles in the pathogenesis of arthritis." (PMID 26293116, 2015). "In the present study, we demonstrated that the severity of arthritis was reduced in GPI-immunized Padi4 KO mice by various changes in immune reactions, including myeloid lineage cells, IL-6, antibodies and Th17 cells." (PMID 26293116, 2015). "WT and Padi4 KO mice both developed arthritis approximately 7 days after the rhGPI immunization and arthritis scores increased between 8 and 14 days after the immunization." (PMID 26293116, 2015). "We herein analyzed the roles of PADI4 in inflammatory arthritis using a glucose-6-phosphate isomerase (GPI)-induced arthritis (GIA) model in Padi4 knockout (KO) mice." (PMID 26293116, 2015). "In summary, the current study shows that PADI2 and PADI4 of the PADI family play a role in promoting arthritis, but whether other members of the PADI family are associated with arthritis remains to be elucidated." (PMID 37020554, 2023). "Similarly, in murine collagen-induced arthritis (CIA), inhibition of PADI4 reduced the formation of NETs and arthritis relief." (PMID 33584645, 2020). "CIA in the Padi4−/− DBA1J mice was characterized by a significantly decreased arthritis score." (PMID 27150598, 2016). "Based on the reduction of the severities of arthritis in Padi4 KO mice, Padi4 suppression could be clinically adopted in human translational medicine." (PMID 26293116, 2015). "Arthritis severity scores were significantly lower in Padi4 KO mice than in WT mice." (PMID 26293116, 2015). "Furthermore, Padi4 KO TNF alpha transgenic (Tg) mice had milder arthritis and less activated CD4+ T cells and some ACPAs than WT–TNF alpha Tg mice." (PMID 26293116, 2015). "Therefore, the reduction observed in arthritis severity in Padi4 KO mice may be explained by factors other than reductions in anti-GPI antibody levels." (PMID 26293116, 2015).
Arthritis (continued). "However, it remains unclear whether the suppression of arthritis in Padi4 KO GIA was relevant to Th17 and/or Th1-mediated inflammatory process, and further investigations are required in this point." (PMID 26293116, 2015). "Conceiveably, our observations with regard to PADI4 and IKZF3 could be interpreted as evidence that putatively common causal SNPs augment gene expression in CD4+ T cells uniquely under the particular biologic and/or environmental circumstances of early arthritis." (PMID 29193869, 2018). "Arthritis severity, serum anti-GPI antibody titers, and IL-6 concentrations were significantly reduced in Padi4 KO mice." (PMID 26293116, 2015). "Inhibitors of peptidyl arginine deiminase 4 that mediates citrullination of histones such as BB-Cl-amidine have shown promise in blocking NET formation and inflammation in experimental models of lupus and arthritis." (PMID 35271686, 2022). "Therefore, the characteristics and roles of ACPAs in mouse models of arthritis are complicated, and will be elucidated, although serum ACPA development was significantly supressed in Padi4 KO GIA mice." (PMID 26293116, 2015). "The arthritis severity score was 5.5 ± 0.84 for the CA1-Tg mice on the 98th day after the first injection, but the score was less than 2 for the wild-type mice and the PADI4-Tg mice under the same conditions." (PMID 23256642, 2012). "In model mice, Padi4 had an effect on arthritis scores but not on the rate of onset." (PMID 27150598, 2016).
autoimmune disease (36 papers, 2014 to 2026). A disorder resulting from loss of function or tissue destruction of an organ or multiple organs, arising from humoral or cellular immune responses of the individual to their own tissue constituents. "It is known that such changes, caused by peptidyl arginine deiminase 4 (PAD4), converts arginine residues to citrullinated residues which may confer autoimmune epitopes on histones, resulting in autoantibodies which may exacerbate autoimmune diseases, such as small-vessel vasculitis and SLE." (PMID 27014266, 2016). "SNPS in genes: PADI4 (rs2240340), STAT4 (rs7574865), CD40 (rs4810485), PTPN22 (rs2476601), and TRAF1 (rs3761847) have been described as risk factors for the development of autoimmune diseases, including RA." (PMID 37108746, 2023). "According to the GWAS Catalog and Immunobase, five of these shared loci (PADI4 at 1p36.13, NAB1 at 2q32.3, COBL at 7p12.1, CCL21 at 9p13.3, and GATA3 at 10p14) have been associated with a single autoimmune disease so far and thus they represent new pleiotropic loci in autoimmunity." (PMID 30572963, 2018). "Furthermore, although most of the recently identified autoimmunity loci are shared among multiple autoimmune diseases, PADI4 is uniquely associated with RA5, which suggests the principle importance of PADI4 in the pathogenesis of RA." (PMID 26293116, 2015). "Protein-arginine deiminase type-4 gene (PADI4), one out of 4 human PADI isoforms, is assigned an important role in triggering autoimmune diseases especially RA due to its ability to citrullination and its implication in the development of autoantibodies." (PMID 33059697, 2020). "Further studies are also needed to more deeply investigate, in RA as well as in other autoimmune disorders where NETosis is involved, the role of PADI3/PADI4 SNPs in affecting enzyme levels and/or activity and possibly histone deimination and NET formation." (PMID 27255888, 2016). "Still, our data shed light on the regulatory effect that PADI4 inhibitors could have on citrullination of proteins, including β-actin, enolase and myelin basic protein (MBP) 4,47,48, that are commonly citrullinated in autoimmune diseases." (PMID 38321148, 2024).
breast carcinoma (35 papers, 2009 to 2026). "Studies have shown that PADI4 is highly expressed in breast cancer and is a tumor susceptibility gene." (PMID 37804426, 2023). "For example, PADI2 and PADI4 can catalyze the guanylation of histones H3 and H4 at the gene promoter, leading to local alterations in chromatin structure and regulation of tumor-associated gene transcription in human breast cancer cells." (PMID 36471887, 2022). "For example, the expression of PADI4 in TN 16 h showed an effect on breast cancer (OR = 1.03, 95%CI = 1.01 to 1.05, p = 2.7 × 10−3)." (PMID 41216857, 2025). "In contrast, although with good instruments in other eQTL datasets, PADI4 expression showed little MR evidence on breast cancer using other eQTL data." (PMID 41216857, 2025). "For instance, mouse breast cancer 4T1 cells that express elevated levels of PADI4 can release cancer extracellular chromatin networks (CECN) both in vitro and in vivo." (PMID 40342932, 2025). "Western blot analysis also detected differential molecular weights of PADI4 in total proteins from whole cells, cell cytoplasm, and cell membranes in breast cancer cells." (PMID 37804426, 2023). "PADI4 was not only localized in the nucleus and cytoplasm of breast cancer cells but was also detected on the cell membrane." (PMID 37804426, 2023). "In breast cancer, PADI4 can also mediate the formation of cancer extracellular chromatin networks (CECNs) and promote lung metastasis of breast cancer." (PMID 37020554, 2023). "After the anti-PADI4 antibody inhibited the expression of cell membrane PADI4, breast cancer cell growth and metastasis were reduced." (PMID 37804426, 2023). "Increased PADI4 expression has been detected in peripheral blood and various tumor tissues, such as gastric cancer, liver cancer, lung cancer, and breast cancer." (PMID 37804426, 2023). "In previous experiments, anti-PADI4 monoclonal antibodies were found to inhibit the progression of breast cancer tumors by inhibiting the citrullination of fibronectin in the extracellular matrix." (PMID 37804426, 2023). "The effect of the PADI4 antibody on the migration of breast cancer cells was examined by Transwell assays." (PMID 37804426, 2023). "PADI4, as a cancer-related gene, is highly expressed in the tissues and blood of breast cancer patients." (PMID 37804426, 2023). "In this study, the subcellular localization of PADI4 in breast cancer cells was examined by immunofluorescence and immunoelectron microscopy." (PMID 37804426, 2023). "To detect the effect of the PADI4 antibody on the viability of breast cancer cells, we performed a CCK-8 assay to assess cell growth." (PMID 37804426, 2023). "After treatment with an anti-PADI4 antibody, the proportion of ATP produced by glycolysis in breast cancer cells decreased, and the aerobic glycolysis in the tumor was reduced." (PMID 37804426, 2023). "In this study, breast cancer cells treated with anti-PADI4 antibodies showed decreased expression of EMT-related proteins, including vimentin, claudin-1, and N-cadherin." (PMID 37804426, 2023). "In this study, we looked across the human genome using ChIP-chip to better define the full repertoire of genes that are regulated by PADI4 in breast cancer cells." (PMID 21655091, 2011). "PADI4 transcripts were detected in gastric adenocarcinomas, lung adenocarcinomas, hepatocellular carcinomas, esophageal squamous cell cancers, breast cancers and breast fibroadenomas as well as their corresponding healthy tissues." (PMID 19183436, 2009). "The PADI4 mRNA level in breast fibroadenomas was lower than that in breast cancers, but higher than that in corresponding healthy tissues." (PMID 19183436, 2009). "In breast cancer and liver cancer, PADI4 can promote angiogenesis and tumor growth." (PMID 37020554, 2023). "Combined with the results of this study, it is further confirmed that PADI4 may be expressed on the cell membrane of breast cancer cells." (PMID 37804426, 2023).
breast carcinoma (continued). "Additionally, PADI4 interacts with Elk-1 at the c-Fos promoter as a transcription factor coactivator in breast cancer." (PMID 37804426, 2023). "This may be another mechanism of action of anti-PADI4 monoclonal antibodies in the treatment of breast cancer." (PMID 37804426, 2023). "It was proved that anti-PADI4 antibody could inhibit the expression of PADI4 on the cell membrane of breast cancer, thus reducing the rate of energy supply by glycolysis in cells, and reducing the metabolism of tumors to a certain extent." (PMID 37804426, 2023). "PADI4 is expressed on the cell membrane in breast cancer cells." (PMID 37804426, 2023). "Furthermore, the effect of the PADI4 antibody on the viability of breast cancer cells was proven using an EdU incorporation experiment." (PMID 37804426, 2023). "In MCF-7 breast cancer cells, silencing the PADI4 gene led to a significant decrease in the nuclear GSK3β level, activation of TGF-β signaling, and induction of the EMT by decreasing E-cadherin and increasing vimentin expression, resulting in more aggressive tumor cells." (PMID 36365233, 2022). "To broaden our knowledge of the regulatory potential of PADI4, we utilized chromatin immunoprecipitation coupled with promoter tiling array (ChIP-chip) analysis to more comprehensively investigate the range of PADI4 target genes across the genome in MCF-7 breast cancer cells." (PMID 21655091, 2011). "By immunohistochemistry and western blotting, we found that PADI4 and CK have similar distributions in the colon, oesophagus, bladder, lung, rectum, stomach and breast cancer, thyroid tumour, oesophageal squamous cell carcinoma, hepatocellular carcinoma, and other non-adenocarcinomas." (PMID 20222985, 2010). "Quantitative PCR and western blot analysis showed higher PADI4 expression in gastric adenocarcinomas, lung adenocarcinomas, hepatocellular carcinomas, esophageal squamous cell cancers and breast cancers (n = 5 for each disease) than in the surrounding healthy tissues." (PMID 19183436, 2009). "Notably, the deletion of Padi4 completely abolished CECN formation in 4T1 cells, decreased the tumor growth rate in allograft models, and reduced lung metastasis associated with 4T1 breast cancer." (PMID 40342932, 2025). "In addition, PADI4 inhibitor can also effectively inhibit the growth of breast cancer bearing mice." (PMID 37804426, 2023). "Therefore, we explored the therapeutic effect of anti-PADI4 monoclonal antibodies on breast cancer." (PMID 37804426, 2023). "Recently, scholars have debated whether knocking out PADI4 gene expression in breast cancer cells can induce the epithelial–mesothelial transformation or enhance cell invasiveness and whether restoring PAD4 expression in MCF-7/ADR cells induces apoptosis and reverses drug resistance." (PMID 36365233, 2022). "It has been reported that PADI4 can promote the invasion and migration of osteosarcoma cells through EMT, and anti-PADI4 inhibits the EMT of breast cancer cells by inhibiting the expression of PADI4 in the cell membrane." (PMID 37804426, 2023). "The subcellular localizations of PADI4 in MDA-MB-231 and MCF-7 breast cancer cells were determined by immunofluorescence, immunoelectron microscopy, and Western blot analysis." (PMID 37804426, 2023). "To explore the effect of the PADI4 antibody on the apoptosis of MDA-MB-231 and MCF-7 breast cancer cells, we conducted flow cytometry." (PMID 37804426, 2023). "The basal subtype but not the luminal or Her2+ breast cancers showed significant correlation of Padi4 expression with distant metastasis-free survival (DMFS)." (PMID 36973439, 2023). "PADI4 can downregulate the expression of NANOG and OCT4, the two main transcription factors of stem cells, by reducing H3R17me2a, leading to a reduction in breast cancer stem cell activity." (PMID 37020554, 2023).
breast carcinoma (continued). "Indeed, it is known that some of the inflammatory stimuli that lead to PADI4 activation in neutrophils, such as chemotactic peptides, incite a calcium influx and a similar mechanism has been attributed to progesterone-dependent PADI2 activation in breast cancer cells." (PMID 35706669, 2022).